SUZ12 (SUZ12 polycomb repressive complex 2 subunit)
Diseases named in the same sentence as SUZ12 in open-access papers (continued):
Sharing a sentence is not in itself a finding about the gene and the disease.
SUZ12 also shares sentences with these, for which no sentence is quoted: Cohen-Gibson syndrome (6 papers); sarcoma (5); mantle cell lymphoma (4); endometrial cancer (3); acute myeloid leukemia (2); Alzheimer disease (2); astrocytoma (2); B-cell lymphoma (2); benign tumors (2); bowel cancers (2); myeloid malignancies (2); neurodegenerative disease (2); stomach cancers (2); acute promyelocytic leukemia (1); adenocarcinoma (1); alveolar rhabdomyosarcoma (1); aplastic anemia (1); autism (1); Cafe-au-lait spot (1); carcinosarcoma (1); central nervous system disorder (1); cholangiocarcinoma (1); chronic lymphocytic leukemia (1); chronic myeloid leukemia (1); cognitive disorder (1); diffuse midline glioma (1); dysplasia (1); endometrial neoplasm (1); esophageal adenocarcinoma (1); esophageal cancer (1).
A further 35 diseases each share a sentence with SUZ12 in 1 paper.